GBP5 (guanylate binding protein 5)
Diseases named in the same sentence as GBP5 in open-access papers (continued):
Sharing a sentence is not in itself a finding about the gene and the disease.
rectum adenocarcinoma (1 paper, 2022). An adenocarcinoma arising from the rectum. "Therefore, we performed a Kaplan-Meier analysis using overall survival in pan-cancer and found that GBP5 was associated with a better short-term prognosis in a majority of cancers such as STAD (Stomach adenocarcinoma), COAD, and READ (Rectum adenocarcinoma)." (PMID 36246628, 2022).
respiratory infections (1 paper, 2022). "We also found that a single gene, GBP5 had the same sensitivity and specificity for TB among total respiratory infections compared to TB score, allowing for potential further simplification of the analytical process." (PMID 34550342, 2022).
Salmonella Infections (1 paper, 2010). Infections with bacteria of the genus SALMONELLA. "IFNG, GBP4, and GBP5 showed dramatic increase post Salmonella infection." (PMID 21172007, 2010).
thymoma (1 paper, 2024). A neoplasm arising from the epithelial cells of the thymus. "Except for thymoma (THYM), GBP5 was significantly and positively associated with CD8+ T cell infiltration in 32 other cancers." (PMID 39355255, 2024).
tularemia (1 paper, 2019). Tularemia is an infection caused by the bacterium Francisella tularensis. "Tularemia vaccine induced higher guanylate binding protein (GBP) responses at Day 2, with upregulation of genes encoding for GBP1P1, GBP5, GBP1, and GBP4 compared to the other vaccines at Day 3 (blue bracket)." (PMID 31878161, 2019).
type 2 diabetes (1 paper, 2025). "For example, GBP5 mRNA levels are significantly higher in South Asian type 2 diabetes patients of Dutch descent compared to those of European descent." (PMID 40788157, 2025). "For example, South Asian type 2 diabetes patients of Dutch descent exhibit higher GBP5 mRNA levels than European-origin patients, correlating with IFN-γ protein levels." (PMID 40788157, 2025).
infection (46 papers, 2015 to 2025). The state of being infected such as from the introduction of a foreign agent such as serum, vaccine, antigenic substance or organism. "To this end, we infected WT, Gbp1–/–, Gbp2–/–, Gbp3–/–, Gbp5–/–, and Aim2–/– mice with F. novicida and monitored their susceptibility to infection." (PMID 35906252, 2022). "Loss of either GBP2 or GBP5 alone was sufficient to render bone marrow-derived macrophages (BMDMs) and mice highly susceptible to infection by B. thailandensis." (PMID 32150572, 2020). "During infection of exogenous pathogenic microorganism, many types of murine Gbps and human Gbp2 and Gbp5 can trigger the host cells’ pyroptosis by activating inflammasome complex containing caspase-1 or caspase-4." (PMID 32731337, 2020). "Based on the results presented in this study, it was concluded that polymorphisms in the candidate genes (GBP1E2, WUR and GBP5) were significantly associated with host resistance to PRRS after experimental infection with the JA142 PRRSV strain." (PMID 32075688, 2020). "Although GBP1 and GBP5 have been demonstrated to be highly associated with increased host resistance against infection with different PRRSV strains, the mechanisms of the increased host resistance to PRRS have not been characterized to date." (PMID 32075688, 2020). "The infection caused a large increase of Gbp2b/Gbp1 and Gbp5 expression, but Gbps levels in both uninfected and infected mice differ among mouse strains indicating influence of genetic factors." (PMID 29467757, 2018). "Infection resulted in approximately 10× upregulation of Gbp2b/Gbp1 and Gbp5 mRNAs in organs of both susceptible and resistant strains, which was most pronounced in skin." (PMID 29467757, 2018). "GBP5 is associated with innate immune response to infection, where AA animals lack GBP5 functionality." (PMID 30355341, 2018). "Follow-up studies identified the putative causative mutation in GBP5, which has been shown to play a role in the innate immune response to infection in mice." (PMID 29132293, 2017). "Consistent with our hypothesis, intranasal infection of mice with B. thailandensis revealed that Gbp2−/−, Gbp5−/−, and GbpChr3-KO mice were highly susceptible to infection." (PMID 32150572, 2020). "Among the genes positively regulated by IRF1 signalling and directly bound by IRF1, we found the already known targets, guanylate-binding protein 2 (Gbp2) and Gbp5 (refs 50, 51), which contribute to clearance of infection as well as Th1-associated genes, including Il12rb1 (refs 1, 36)." (PMID 28497800, 2017). "In contrast to GBP5, however, which is primarily induced by type II IFNs, they reported that IFITMs are mainly induced by type I IFNs that are increased in response to infection." (PMID 40333975, 2025). "This review provides a comprehensive analysis of the diverse functions of GBP5 in various diseases, highlighting its potential as a biomarker and therapeutic target in infection, tumorigenesis, and immune regulation." (PMID 40788157, 2025). "Collectively, GBP5 is integral to immune defense, and its diverse mechanisms offer promising avenues for infection control." (PMID 40788157, 2025). "GBP5, as an effector molecule activated by pathogen infection, plays an important biological role in generating immune response." (PMID 40075517, 2025). "In PPROM, GBP5 is markedly upregulated in placental tissues, suggesting its contribution to preterm birth by mediating infection and inflammation." (PMID 40788157, 2025). "These discrepancies likely reflect distinct stages of infection, suggesting GBP5 as a promising biomarker for monitoring disease progression and therapeutic response." (PMID 40788157, 2025). "During infection, GBP5 triggers GSDMD-mediated pyroptosis by facilitating caspase-11 activation, influencing pathogen invasion." (PMID 40788157, 2025).
infection (continued). "Induced primarily by interferons, GBP5 exerts diverse effects within infection, inflammation, and tumor microenvironments, modulating host immune responses to pathogens through various mechanisms (7, –, 9)." (PMID 40788157, 2025). "We found that both IRF1 and GBP5 reduced infection in NHSK-1-VP30s, demonstrating that the EBOV-inhibitory capabilities of these ISGs extends to human keratinocytes." (PMID 41472248, 2025). "GBP5 plays a pivotal role in the pathogenesis of diverse diseases, including infections, cancers, immune disorders, and inflammatory conditions, where its expression levels exhibit dynamic changes and potential immunoregulatory functions." (PMID 40788157, 2025). "GBP5 (guanylate binding protein 5) plays an important role in the assembly of the NLRP3 inflammasome in response to infection and a variety of inflammatory disease processes." (PMID 39924511, 2025). "(iii) Targeted Therapies: Developing precision interventions for infections, tumors, immune, and inflammatory diseases by modulating GBP5 activity." (PMID 40788157, 2025). "In this regard, C57BL/6 wild-type, GBP2-/-, GBP5-/- and GBPchr3-/- mice were infected with B. abortus and monitored for two weeks post-infection." (PMID 38404575, 2024). "Remarkably, GBP5 presents increased induction 2 hours post-infection and it remains with the highest expression level in all time points evaluated (up to 17 hours)." (PMID 38404575, 2024). "Consistent with reduced IFNγ expression, the mRNA induction of Nos2, Gbp1, Gbp2, Gbp4, Gbp5, Ido1 and Acod1 was severely impaired in the spleens of Myd88−/− mice after intraperitoneal infection." (PMID 36479617, 2023). "As well as the cytotoxic effects of NO, guanylate binding protein (GBP) genes, including Gbp5, are known to be important for controlling infection with T. gondii." (PMID 34835465, 2021). "Gbp5 protein levels were also increased upon CTG or GT1 infection of naive macrophages, although to a lesser extent than IFN-γ treatment in wild-type BMDMs." (PMID 30154263, 2018). "Infection increased the expression of Gbp2b/Gbp1 and Gbp5 in organs of tested mice, the highest increase was observed in skin." (PMID 29467757, 2018). "Taken together, the results indicate that downregulation of mmu-miR-21a-5p induced by infection increases GBP5 levels and decreases IL-10 expression thus contributing to bacterial control in host cells." (PMID 29942317, 2018). "The increased expression of Gbp2b/Gbp1 and Gbp5 in clinically asymptomatic mice reveals the price exacted from the organism by a dormant infection." (PMID 29467757, 2018). "Expression of Gbp5 was strongly induced upon infection with T. gondii, while Gbp2 and Gbp7 were induced at lower levels, and no substantial change was seen in Gbp1 or Irga6." (PMID 30154263, 2018). "Gbp2 and Gbp5 were among the top upregulated ISGs in IECs during infection." (PMID 40885187, 2025). "Interestingly, Gbp2 and Gbp9 were also elevated following infection with both L. mexicana and L. amazonensis, while Gbp5 trended towards an increase following infection with both species similar to L. major infection." (PMID 40631203, 2025). "To investigate whether individual GBPs are responsible for IRGB10 recruitment, we overexpressed IRGB10 and one GBP at a time (GBP1, GBP2, GBP3, GBP5 or GBP7) in LA-4 cells followed by infection with F. novicida." (PMID 35906252, 2022). "This SNP was previously associated with host response to experimental infection of nursery pigs with PRRSV and is in high LD with the putative causative mutation for this effect in the GBP5 gene, which plays a role in immune regulation and in mediating inflammatory immune response in the mouse." (PMID 35100362, 2022). "Herein, we hypothesize that in initial phase of infection host cells can downregulate miR-21a-5p expression to reduce IL-10 and increase GBP5 expression thus resulting in improved control of Brucella replication." (PMID 29942317, 2018).
infection (continued). "All tested strains except CcS-5 and OcB-9 exhibited significantly higher expression of Gbp2b/Gbp1 and Gbp5 in skin after infection, irrespective of their susceptibility or resistance status." (PMID 29467757, 2018). "Additionally, Gbp5 expression was induced upon infection and the enhanced clearance of CTG strain parasites was reversed in Gbp5−/− macrophages." (PMID 30154263, 2018). "However, only GBP5 was identified as DE across multiple time points post infection (FDR < 0.05) and across all time points (FDR = 0.051)." (PMID 26016888, 2015). "Further research is needed to delineate GBP5’s regulatory pathways in diverse cancer types and to elucidate its evolving role within the tumor microenvironment, offering opportunities for advanced cancer immunotherapies and infection-related cancer interventions." (PMID 40788157, 2025). "Interestingly, GBP5 is completely dispensable for inflammasome activation during popB infection." (PMID 30062052, 2018). "We detected some significantly upregulated proteins upon infection: IRG1, GBP5, ICAM1, ACSL1, and PDL1 independently on the presence or absence of SLAMF1." (PMID 39000601, 2024). "TVs expressing sgRNAs targeting known RFs like TRIM5, IFI16, IFITM2, SAMHD1, GBP5 and IFITM1 were enriched after 15 and 20 days post-infection confirming that targeting RFs provides a selection advantage to the respective viruses." (PMID 38714682, 2024). "Since many antiviral factors including tetherin and GBP5 are IFN-inducible, infections were performed in the absence and presence of IFN-β." (PMID 38714682, 2024). "Guanylate binding protein 1 (GBP1) and guanylate binding protein 5 (GBP5) are two member of the GBP family and mediate cellular response to IFNγ in infection and inflammation." (PMID 35187081, 2022). "Transcriptomic profiling of MPXV-infected MK2 cells at 7 h post-infection further revealed the upregulation of multiple guanylate-binding protein (GBP) family members, including GBP3, GBP5, GBP6, and GBP7, highlighting a broader antiviral gene program downstream of type I IFN–IRF1 signaling." (PMID 41225161, 2025). "Upon infections with furin-dependent viruses such as HIV, this may provide a selection advantage as it increases the expression of GBP5, thereby impairing furin-mediated activation of viral glycoproteins." (PMID 40333975, 2025). "For further revealing the role of KRT9 in the GBP5 anti-RSV process, endogenous KRT9 knockdown HEK293T cells were overexpressed with the wild-type or a 202–302 deletion mutant of KRT9 and infected with RSV at 0.1 multiplicity of infection." (PMID 39835811, 2025). "Our results displayed some proteins (IRG1, GBP5, PDL1, and ICAM1) correlated in all the conditions forming a unique section, in combination with other proteins in each specific condition, such as RSAD2, presented only in the Y infections." (PMID 39000601, 2024). "Besides GBP5, we also studied GBP2, due to its high expression profile and its aggregation near BCVs during infection." (PMID 38404575, 2024). "Importantly, we found that WT, Gbp1–/–, Gbp2–/–, Gbp3–/–, Gbp5–/–, and Aim2–/– BMDMs all released similar levels of IL-1β, IL-18 and LDH in response to infection with F. novicida in the presence of E. coli LPS." (PMID 35906252, 2022). "Consistent with the microarray, protein levels of GBP2 and GBP5 were reduced in the Ifnar1−/−, Irf9−/−, Irf1−/−, Trif−/−, and Irf3−/−Irf7−/− macrophages that undergo extensive cell-cell fusion during infection but not in Myd88−/−." (PMID 32150572, 2020). "Finally, heightened induction of Gbp2, Gbp4, Gbp5, Gbp6, and Ip10 in Sts−/− cells relative to wild type cells was observed following both IFNγ treatment alone and LVS infection of IFNγ‐treated cells." (PMID 32841534, 2020). "Mice lacking GBP2, GBP5, or multiple GBPs on chromosome 3 (GBP2, GBP2b (GBP1), GBP3, GBP5, GBP7) were significantly more susceptible to infection, revealing a critical role for these proteins in restricting bacterial infection." (PMID 32150572, 2020).
infection (continued). "Expression of Gbp5 in skin of uninfected CcS-20 exceeded level of both parents but was significantly higher only than the parental strain STS after 8 weeks of infection." (PMID 29467757, 2018). "In addition, infection of macrophages leads to upregulation of GBPs, and the clearance of type III parasites was partially reversed in Gbp5−/− macrophages." (PMID 30154263, 2018). "GBP5 plays a role in the innate immune response during infection, and animals that have the AA genotype appear to produce no functional GBP5." (PMID 27324857, 2016). "In addition, studies have shown that expression of GBP1-3, GBP5, and GBP7 in mice is significantly upregulated 4 h after infection with B. abortus, with GBP5 expression beginning to rise as early as 2 h post-infection and remaining the highest among all GBPs at each time point." (PMID 40606156, 2025). "It is notable however, that although GBPs did not sensitize to IFITMs, combining GBP5 in producer cells with IFITM1 in target cells led to an almost complete inhibition of Wuhan-Hu-1 infection when compared with infection in the absence of these restriction factors." (PMID 36693093, 2023). "GBP5 was induced by IFN-γ, could serve as a marker of IFN-γ-induced classically activated macrophages and the substitute indicator of IFN-γ, which can directly suppress tumorigenesis and infection and/or can modulate the immunological status in cancer cells." (PMID 31169496, 2019). "Although most Gbps are known to target invading pathogens, Gbp5 can also assemble the NLRP3 inflammasome in the absence of infection, and within infected cells, such assembly could conceivably take place on or near the pathogen vacuole." (PMID 30154263, 2018). "As early as 2 hours post-infection, we observed significantly increased GBP2, GBP5 and GBP7 mRNA levels compared to non-infected cells." (PMID 38404575, 2024). "However, in contrast to previous studies, they found that GBP5 also interfered with the function of the Env glycoproteins from vesicular stomatitis virus (VSV) and SARS-CoV-1, which do not require furin to mediate infection." (PMID 39404361, 2024).
cancer (33 papers, 2015 to 2026). A tumor composed of atypical neoplastic, often pleomorphic cells that invade other tissues. "Consistently, GBP5 expression is positively associated with infiltration levels of immune cells in diverse cancer types." (PMID 42204045, 2026). "These insights emphasize GBP5’s potential as a diagnostic marker, therapeutic target, and prognostic indicator in cancer." (PMID 40788157, 2025). "Here, we found that GBP5 knockdown decreased several chemotherapy resistance-associated cancer stemness markers such as ALDH1A1, ALDH1A2, CD44, CD166, and ABCG2." (PMID 34439200, 2021). "Additionally, the association of GBP5 with CD8+ T cell infiltration was investigated across 33 cancers." (PMID 39355255, 2024). "In summary, GBP5 exhibits complex mechanisms in cancer, including regulation of pyroptosis, inflammasome activation, cell proliferation, invasion, immune evasion, and microenvironment remodeling." (PMID 40788157, 2025). "This review provides a systematic overview of GBP5 research, encompassing its roles in infectious diseases, cancer, and immune-mediated disorders." (PMID 40788157, 2025). "The role of GBP5 in cancer has attracted increasing attention due to its involvement in tumor immune escape and regulation of the tumor microenvironment." (PMID 40788157, 2025). "Not only due to its nature of pyroptotic cell death promoter in cancer cell, GBP5's capability of promoting M1 macrophage polarization potentially make the TME more immune-responsive, thus assisting the efficacy of immunotherapy." (PMID 38817865, 2024). "In particular, GBP5 has emerged as an immune regulator and a biomarker for inflammation and cancers." (PMID 39355255, 2024). "In this research, we discovered a benign biomarker GBP5 in OC, which was commonly considered as an inflammatory modulator and hardly correlated with cancer research." (PMID 38817865, 2024). "The pan-cancer analysis presented a common positive correlation between M1-type macrophage polarization and GBP5 expression." (PMID 38817865, 2024). "We also used ssGSEA or CIBERSORT method to obtain the infiltration of immune cells in CRC or pan-cancer and compared its correlation with GBP5 expression." (PMID 36246628, 2022). "Although this is a preliminary result, it lays the foundation for the future study of GBP5 in cancer." (PMID 36246628, 2022). "The correlation between GBP5 and TMB or MSI in pan-cancer was compared to better understand the predictive role of GBP5 in ICB response." (PMID 36246628, 2022). "In most other cancers, GBP5 is also elevated in tumors compared with normal tissues and is associated with a better prognosis." (PMID 36246628, 2022). "This is the first bioinformatics study of GBP5 in pan-cancer and the first analysis of GBP5 using scRNA-seq." (PMID 36246628, 2022). "Further study for the molecular mechanism of GBP5-associated EGFR, STAT1, chemotherapy resistance-associated cancer stemness markers, and PIM1 is warranted in OSCC." (PMID 34439200, 2021). "Moreover, GBP5 upregulation may be associated with cancer progression, e.g., metastasis, in TNBC." (PMID 33916322, 2021). "This review provides a comprehensive synthesis of GBP5 functions across infectious diseases, cancer, immune disorders, and inflammation, with dedicated analysis of its context-dependent functional variability in distinct immune landscapes, genetic backgrounds, and disease progression stages." (PMID 40788157, 2025). "Single-cell RNA sequencing might dissect TME-GBP interactions at granular resolution, revealing cell-specific roles—e.g., GBP5 in tumor-infiltrating lymphocytes versus cancer cells, monitorable through spatial transcriptomics or CyTOF analysis." (PMID 40564939, 2025). "Similar results were observed not only in OC but also in other 25 cancer types (cancer types without C2-type samples were excluded in this analysis), indicating that the positive correlation between high GBP5 expression and the C2 phenotype can be considered a pan-cancer commonality." (PMID 38817865, 2024).